BRAF (B-Raf proto-oncogene, serine/threonine kinase)
Diseases named in the same sentence as BRAF in open-access papers (continued):
Sharing a sentence is not in itself a finding about the gene and the disease.
melanoma (continued). "Currently, there has been remarkable progress in understanding melanoma pathogenesis, and numerous studies have now shown the correlation of BRAF and NRAS mutation status with clinical outcome and immune and targeted therapy strategies in melanoma." (PMID 29349077, 2017). "Some studies found no prognostic impact of mutation status and other studies demonstrated that BRAF-mutant or NRAS-mutant melanoma patients had poorer overall survival." (PMID 29349077, 2017). "In contrast BRAFi exert a paradoxical tumor promoting effect in RAS mutated melanomas where they induce the allosteric activation of heterodimeric complexes formed by mutated and wild-type BRAF monomers." (PMID 28118616, 2017). "The functional dependence of BRAF mutation probability according to the four most influential parameters (age, center, melanoma subtype, and UV exposure) was visualized." (PMID 29176861, 2017). "Overall, BRAF mutation rate in 100 primary melanoma samples was 67,3% when analyzed by PNA, and 59% when the V600E mutation was assessed using the VE1 specific antibody for IHC staining." (PMID 28039443, 2017). "Significantly, the expression of BRAF splice variants is insufficient to confer MEK inhibitor resistance in melanoma." (PMID 28503307, 2017). "Altogether, our data suggested that the coexistence of EZH2 gain and the BRAF V600E mutation was prevalent in melanoma, especially mucosal subtype." (PMID 29202777, 2017). "Consistently, resistance of melanomas to BRAF and/or MEK inhibitors is associated with increased CD20 and IGF-1 transcript levels in tumors and IGF-1 expression in tumor-associated B cells." (PMID 28928360, 2017). "TERT promoter mutations when combined with BRAF/NRAS mutations correlate with adverse outcome in adult melanoma." (PMID 28378855, 2017). "Both BRAF V600E mutation and Notch signaling pathway should be studied as bioactive agents against melanoma." (PMID 26884744, 2016). "Gain of function mutations in oncogene BRAF has been observed in approximately 60% of melanoma tumors." (PMID 26517521, 2016). "The identification of activating somatic mutations in serine-threonine protein kinase BRAF (BRAFV600E) in 50% of patients with advanced melanoma offered the opportunity to develop oncogene-targeted therapies for this tumor." (PMID 27563819, 2016). "In the present study we investigated sorafenib, a RAF inhibitor in combination with fisetin on cell invasion, EMT and lung metastasis of BRAF-mutated melanoma cells." (PMID 26517521, 2016). "Trametinib showed favorable clinical efficacy in a phase III trial in treatment of BRAF-mutated melanoma patients in comparison to chemotherapy [median progression-free survival (PFS) was 4.8 vs 1.5 months (p < 0.001); 6 months OS was 81 vs 67 % (p < 0.01)]." (PMID 26860843, 2016). "BRAF mutations are highly prevalent in melanomas, suggesting that this type of tumor, between other pathways, is regulated by the MAPK pathway." (PMID 26898917, 2016). "For instance, Ras/Raf/Mek signalling has come to the fore with the finding that up to 50% of melanomas have a BRAF mutation and up to 30% have a NRAS mutation, with resulting inhibitors targeting BRAF specifically and MEK signalling in general." (PMID 27384486, 2016). "The TCGA project with 228 melanoma samples detected BRAF mutations in 51% and CRAF mutations in 4% of the melanoma cases." (PMID 27273450, 2016). "The V600E mutation accounts for the majority of these mutations, especially in melanoma where approximately 60–70 % cases of melanoma patients have BRAF mutations, and about 90 % of these are V600E." (PMID 27094161, 2016). "Herein we demonstrate a microfluidic approach for melanoma cell capture and subsequent on-chip evaluation of BRAF mutation status." (PMID 26815318, 2016). "Recently the ErbB3 receptor has been shown by us and by others to act as a central node in the promotion of adaptive survival of BRAF mutated melanoma cells early upon drug exposure." (PMID 27461275, 2016).
melanoma (continued). "In melanoma, driving oncogenic mutations in v-Raf murine sarcoma viral oncogene homolog B (BRAF) and neuroblastoma rat sarcoma viral oncogene homolog (NRAS) are found in about 40% and 20% of tumors, respectively." (PMID 26771141, 2016). "While BRAF inhibitors have displayed a rapid and dramatic response rate in BRAF mutated melanoma patients, most of these patients eventually relapse." (PMID 27285585, 2016). "In conclusion, this analysis confirmed known factors such as age and type of primary melanoma as variables correlating with the probability to carry a BRAF mutation." (PMID 27150060, 2016). "The majority of human melanomas bears BRAF mutations and thus is treated with inhibitors of BRAF, such as vemurafenib." (PMID 26871475, 2016). "The development of keratoacanthoma and cutaneous squamous-cell carcinomas in melanoma patients treated with the selective BRAF inhibitor vemurafenib has been linked to the presence of frequent mutations in RAS, particularly HRAS." (PMID 27999416, 2016). "An example is a clinical trial of vemurafenib, a BRAF inhibitor in multiple non-melanoma cancers with BRAF V600 mutations." (PMID 27793177, 2016). "Vemurafenib is a potent inhibitor of the kinase domain in mutant BRAF, a mutation carried by half of melanomas." (PMID 26767073, 2016). "Oncogene BRAF, which is constitutively activated also in our melanoma model Rel3 was implicated to be directly involved in reprogramming of cellular metabolism." (PMID 27175734, 2016). "We have shown that wild type RASA1, but not identified mutants, suppresses soft agar colony formation and tumor growth of BRAF mutated melanoma cell lines via its RasGAP activity toward R-Ras (related RAS viral (r-ras) oncogene homolog) isoform." (PMID 26993606, 2016). "Metastatic melanoma patients harboring this hot spot mutation can be effectively treated with BRAF inhibitors alone or in combination with MEK inhibitors because this genetic alteration is predictive to therapeutic response." (PMID 27863476, 2016). "With the intensive interest of targeted therapy, great relief came with the initial clinical success of BRAF inhibitors (BRAFi), targeting the V600E mutation in melanoma such as vemurafenib (or PLX4032)." (PMID 27896217, 2016). "Alterations in the tumor suppressor NF1, a negative effector of Ras, were present in a thin melanoma (M16, non-sense mutation and copy loss) harboring wt BRAF and in a thick melanoma (M9, non-sense mutation) with BRAF V600E." (PMID 27095580, 2016). "We found that NRAS-mutant melanoma cells were significantly more resistant to the cytotoxic effects of DNA replication stress-inducing drugs compared to other genotypes (BRAF-mutant, NF1-deficient, or triple wild-type)." (PMID 27608486, 2016). "In 2013 the MEK inhibitor Trametinib was approved for the treatment of melanoma patients with unresectable or metastatic melanoma with BRAF mutations." (PMID 27376062, 2016). "Common genes associated with aggressive melanoma include BRAF, with these mutations comprising the majority of melanoma cases (37–50%), followed by NRAS (13–25%) and NF1 (11.9%)." (PMID 27829238, 2016). "Both HDRA and PDX models derived from the BRAF-mutated melanoma showed significant response to BRAF and MEK inhibitors, and those derived from the NRAS-mutated melanoma showed a significant response only to the MEK inhibitor pimasertib." (PMID 26909610, 2016). "Mutations as well as deletions of PTEN are found in approximately 30% of melanoma cell lines and are frequently associated with mutations in BRAF." (PMID 27833586, 2016). "β-catenin also regulates the metastatic potential (in a PTEN loss/BRAF activating mutation context-dependent manner) and differentiation of melanomas." (PMID 27531891, 2016). "The MAPK pathway plays a major role in melanoma proliferation and survival and is activated in the majority of melanoma tumors through mutations in BRAF and to some extent in NRAS." (PMID 27449293, 2016).
melanoma (continued). "Our data suggest that 22.1% of BRAF mutations in NZ melanomas were non-V600E mutations, which is similar to the 25% figure obtained in a study of 1,112 cases of melanoma using pyrosequencing or Sequenom MassARRAY." (PMID 27191502, 2016). "Altogether, oncogenic BRAF V600E mutation in melanoma cells was shown to control a network of >20 miRNAs with combinatorial functions to modulate the expression of key cancer regulatory genes." (PMID 26646588, 2016). "Analyses of larger patient cohorts are required to validate the use of ZEB1 as a predictive marker in order to stratify BRAF‐mutated melanoma into MAPKi‐sensitive and MAPKi‐resistant subgroups." (PMID 27596438, 2016). "Most malignant melanomas have mutation of the BRAF gene leading to constitutive activation of downstream signaling in the mitogen-activated protein (MAP) kinase pathway." (PMID 26884744, 2016). "BRAF inhibitors can extend progression‐free and overall survival in melanoma patients whose tumors harbor mutations in BRAF." (PMID 26365896, 2016). "Treatment with trametinib, compared with chemotherapy, significantly reduced the risk of death and risk of disease progression in patients with BRAF V600E/K mutation–positive advanced melanoma or MM." (PMID 27172483, 2016). "No statistically significant mutational associations with Breslow thickness were observed, although a slightly higher percentage of BRAF mutations occurred in melanomas >4mm thick." (PMID 27191502, 2016). "Currently, the standard of care in BRAF-mutated advanced melanoma is a combination of BRAF and MEK inhibitors." (PMID 26930506, 2016). "Some melanomas with BRAF mutations demonstrate intrinsic resistance, in that there is very little response even initially to BRAF inhibition." (PMID 26871475, 2016). "Materials and methods: BRAF-mutated melanoma cell lines M14, A375 and LOX-IMVI (BRAF V600E), WM115 and WM266 (BRAF V600D) were exposed to BRAFi and/or MEKi treatments at different times." (PMID 27461275, 2016). "Both A375 and WM266.4 human melanoma cell lines harbour BRAF mutations and are sensitive to PLX4720." (PMID 26414886, 2016). "The effects of UV radiation are well known, and several mutations, such as CDKN2A and BRAF mutations, have been shown to correlate with malignant melanoma." (PMID 27999823, 2016). "PTEN deletions co-exist with BRAF mutations in approximately 30% of melanomas, leading to the concurrent activation of the MAPK and PI3K/AKT pathways." (PMID 27655717, 2016). "To demonstrate on-chip detection of BRAF mutations across the melanoma cell population, we spiked 100 LM-MEL-6 (BRAFV600E) and LM-MEL-53 cells (BRAF wild type) in PBS, and captured them under optimal AC-EHD force." (PMID 26815318, 2016). "The BRAF mutation was detected on metastatic sites in 35 pts and on the primary melanoma in 5 cases." (PMID 26981153, 2016). "One of the therapeutic approaches that provides clinically important benefit for patients with disseminated melanoma whose tumors contain the V600 mutation in the BRAF gene is based on the inhibition of the MAP kinase pathway with BRAF inhibitors." (PMID 27708249, 2016). "Its role in melanoma has been described but molecular actors, the influence of BRAF mutations on cell metabolism and molecules involved in bioenergetic transformation, have not been clearly defined." (PMID 27461275, 2016). "Thirty-three tumors (23.6%) harboring BRAF mutations were identified as superficial spreading melanomas (SSM) compared with 26 (20.1%) melanomas with NRAS mutations." (PMID 27191502, 2016). "We did not observe similar changes in mRNA levels of E2F2 or its target genes after IFI6 knockdown in BRAF-mutant or NF1-deficient melanoma cell lines." (PMID 27608486, 2016).
melanoma (continued). "On the other hand, by screening for p15-inducing compounds, we have discovered the MEK inhibitor trametinib, which has recently been approved for the treatment of BRAF-mutated melanoma by the US Food and Drug Administration, EU, and others." (PMID 27148684, 2016). "This single-arm, open-label, phase II study evaluated a sequencing strategy with these two agents in previously untreated patients with BRAF-mutated advanced melanoma." (PMID 27532019, 2016). "This study highlights the potential therapeutic interest of NS1 inducing cell death by triggering a selective ER stress and incomplete autophagy in melanoma cells harbouring wt and BRAF mutation." (PMID 27756874, 2016). "Activating mutations in the BRAF protein kinase are the most common genetic alterations in melanoma, found in around 40 % of tumors." (PMID 26907172, 2016). "A prominent mechanism of acquired resistance to BRAF inhibitors in BRAFV600-mutant melanoma is associated with the upregulation of receptor tyrosine kinases." (PMID 27648299, 2016). "BRAF is mutated in approximately 50% of melanomas; 80–90% of these activating mutations involve a single substitution of valine in position 600 with glutamic acid (V600E)." (PMID 27833586, 2016). "The low frequency of BRAF mutations associated with UV-independent carcinogenesis and oral anatomical distribution of canine melanomas supports the dog as a spontaneous model for investigation of non-UV-associated human melanomas." (PMID 29056717, 2016). "Vemurafenib produced improved rates of OS and PFS in patients with previously untreated melanoma with the BRAF V600E mutation." (PMID 26767073, 2016). "Patients with an acrolentiginous melanoma, lentigo maligna melanoma, mucosal or an ocular melanoma being of age 44+ have only a probability of carrying a BRAF mutation of only 22%." (PMID 27150060, 2016). "Approximately 40–50% of melanomas harbor activating mutations of the RAS/RAF axis, including the V600E BRAF mutation in an oncogene known to be critical for melanoma proliferation and survival through its role in activating the RAF/MEK/ERK pathway." (PMID 27764776, 2016). "In the present study, we evaluated the efficacy of S. typhimurium A1-R alone and in combination with TEM on a PDOX model for melanoma with the BRAF-V600E mutation." (PMID 27835903, 2016). "Melanoma is a heterogeneous tumor, with most patients harboring mutations in the BRAF or NRAS oncogenes, leading to the overactivation of the MAPK/ERK and PI3K/Akt pathways." (PMID 27833586, 2016). "A major breakthrough in the understanding of the pathogenesis of melanoma came with the discovery that a large number of melanomas harbor activating mutations in BRAF." (PMID 26784231, 2016). "In just one example, the wide array of resistance mechanisms in BRAF-mutant melanoma to RAF inhibitors (RAFi) include mutations in NRAS, MEK and ERK and the amplification and alternative splicing of BRAF." (PMID 27738492, 2016). "The expression levels of CCL2 and HIF1A were positively correlated in BRAF-mutated melanoma tumor specimens, further supporting an association between HIF1 and CCL2." (PMID 26684239, 2016). "The likelihood for patients being younger than 44 years and having a tumor thickness of less than 0.62 mm to carry a BRAF mutation is 35% whereas for patients with a melanoma with a thickness of 0.62 mm or above is 62%." (PMID 27150060, 2016). "In melanoma, BRAF represents the most commonly mutated gene in the MAPK signaling cascade where 90% of tumors carry a valine to glutamic acid transition at codon 600 (V600E) that renders BRAF constitutively active and hyperactivates the MAPK cascade." (PMID 26999821, 2016). "About 40–60% of melanoma patients exhibit a BRAF mutation occurring with a ninety percent frequency substitution of glutamate for valine at amino acid 600 (i.e., V600E mutation)." (PMID 27285585, 2016).
melanoma (continued). "For example, while melanoma patients harboring BRAF V600E mutation respond well to BRAF inhibitors, colon cancer patients with the same mutation often don’t due to the feedback activation of EGFR and its associated signaling pathway." (PMID 26916442, 2016). "A complete surgical resection was performed, and the diagnosis of malignant melanoma, with BRAF mutation, was obtained after histology exam." (PMID 27586680, 2016). "Hyperactivity and over-expression of RhoA and hyper-activated mutated BRAF have been observed in human cancers, including melanoma." (PMID 26828592, 2016). "The approach is also shown to capture differences in the immune-cell networks of BRAF versus NRAS mutated metastatic melanomas, and the dynamic changes in resistance to targeted kinase inhibitors in MAPK signalling." (PMID 27377892, 2016). "In the present study, analysis of sorafenib treated BRAF-mutated melanoma cells and xenograft tumor tissues showed reduced protein expression of mesenchymal marker proteins (N-cadherin, vimentin and fibronectin)." (PMID 26517521, 2016). "Approximately 75% of melanomas have known driver oncogenic mutations in BRAF, NRAS, GNA11 or GNAQ, while the mutations providing constitutive oncogenic signaling in the remaining melanomas are not known." (PMID 27273450, 2016). "Comparing BRAF mutation rates in NZ melanomas with the melanoma mutation data from TCGA, we found that BRAFV600E mutations occurred in a relatively smaller percentage of NZ melanomas than in TCGA, although this was not significant." (PMID 27191502, 2016). "Limited success has been achieved in treating melanomas with agents that target the BRAF-V600E mutation observed in about 50% of melanomas and with ipilumumab, but none of these have been curative." (PMID 27285585, 2016). "In contrast, the expression of the BRAF proto-oncogene (the gene that is most commonly mutated in melanoma) was augmented by melanoma metastasis and this stimulation was decreased by Poly(I:C)." (PMID 27198666, 2016). "In our study, loss of RASA1 triggered activation of R-Ras and Ral-A and R-Ras was required to drive colony formation driven by RASA1 inactivation in melanoma cells with BRAF mutation." (PMID 26993606, 2016). "The computational approach here detected notable differences in the immune-cell networks between BRAF and NRAS mutated metastatic melanomas, in addition to BRAF mutated melanomas that have acquired resistance after combined MAPKi therapy." (PMID 27377892, 2016). "Our study provides insight into the microenvironment-mediated mechanisms underlying drug resistance and delineates the implications associated with optimal dosing and scheduling of combination therapy for melanoma patients with BRAF mutations." (PMID 26928089, 2016). "More evidences are needed to confirm the role of BRAF inhibitors in BRAF mutated melanoma patients with LMC." (PMID 27399673, 2016). "On September 4, 2014 pembrolizumab was approved by FDA for the treatment of advanced melanoma in patients previously treated with ipilimumab or a BRAF inhibitor in BRAF V600 mutation positive patients." (PMID 28018338, 2016). "Expression of these EMT-inducers is regulated by MAPK and PI3K signaling, therefore, the effect of fisetin, sorafenib and their combination on the expression of these EMT-inducing transcription factors in BRAF-mutated melanoma cells was also determined." (PMID 26517521, 2016). "Human melanomas (n = 17) of different genotypes (mutated BRAF, NRAS, amplified cKIT and wild type) were successfully engrafted in mice then amplified by successive transplantations." (PMID 26909610, 2016). "The present study used a patient-derived orthotopic xenograft (PDOX) nude-mouse model of melanoma with a BRAF-V600E mutation to determine the efficacy of temozolomide (TEM) combined with tumor-targeting Salmonella typhimurium A1-R." (PMID 27835903, 2016).